CNTN1 (contactin 1)
Diseases named in the same sentence as CNTN1 in open-access papers (continued):
Sharing a sentence is not in itself a finding about the gene and the disease.
myopathy (2 papers, 2011 to 2024). A disease of the muscle in which the muscle fibers do not function properly. "As more alleles of CNTN1 are identified in humans, it will be interesting to see if the severe myopathy is a reproducible feature of the phenotype, or if it is selectively found in truncating mutations like S291fsX296." (PMID 22242131, 2011). "For the CNTN1 mutation to not be the causative factor, one would have to invoke a second closely linked mutation that results in congenital lethal myopathy before a later CNTN1 phenotype could arise." (PMID 22242131, 2011). "Their phenotype was lethal myopathy because of decreased levels of CNTN1 at neuromuscular junctions, leading to disrupted communication between muscles and nerves." (PMID 38225934, 2024). "If the primary phenotype of CNTN1 mutations in people is a myopathy, then understanding why this is not a prominent aspect of the mouse phenotype may lead to possible therapeutic strategies for CNTN1-related diseases." (PMID 22242131, 2011). "Therefore, the Cntn1 mutant mice do not show evidence for a myopathy, but instead the phenotype is likely to be caused by dysfunction in the nervous system." (PMID 22242131, 2011). "Mice lacking Cntn1 do not have obvious myopathy or defects in syntrophin and dystrobrevin localization at NMJs, and NMJ morphology is normal in the mutant animals." (PMID 22242131, 2011).
psychiatric disorder (2 papers, 2018 to 2019). A disorder characterized by behavioral and/or psychological abnormalities, often accompanied by physical symptoms. "CNTN1 has also trans-diagnostic evidence for involvement in psychiatric disorders." (PMID 30755720, 2019). "Whilst CRTAP and GLB1 have not previously shown association with psychiatric disorders, both genes are members of the CNTN1 PPI subnetwork." (PMID 29317602, 2018).
genetic disease (1 paper, 2019). "The results from our functional analyses indicate abnormal Nfasc155 interaction with CNTN1 and CASPR1 as an important disease mechanism in the NFASC-related genetic disease." (PMID 31501903, 2019).
hematological tumors (1 paper, 2025). "CNTN1 serves as a protective factor in six types of hematological tumors." (PMID 41048997, 2025).
CNTN1 also shares sentences with these, for which no sentence is quoted: colorectal cancer (3 papers); brain tumor (2); esophageal squamous cell carcinoma (2); liver cancer (2); lymphoma (2); memory impairment (2); neuromyelitis optica (2); pemphigus (2); squamous carcinoma (2); amyotrophic lateral sclerosis (1); Anorexia (1); autoimmune encephalitis (1); autonomic dysfunction (1); autosomal recessive mental retardation type 13 (1); axonal neuropathy (1); Brain atrophy (1); chronic atrophic gastritis (1); colon adenocarcinoma (1); Compton-North congenital myopathy (1); demyelinating disease (1); demyelination (1); Duchenne muscular dystrophy (1); dyslexia (1); dystroglycanopathies (1); endometriosis (1); epilepsy (1); Epileptic encephalopathy (1); focal segmental glomerulosclerosis (1); fracture (1); Friedreich ataxia (1).
A further 33 diseases each share a sentence with CNTN1 in 1 paper.